FLT3 (fms related receptor tyrosine kinase 3)
Diseases named in the same sentence as FLT3 in open-access papers (continued):
Sharing a sentence is not in itself a finding about the gene and the disease.
leukemia (continued). "Finally, we also wished to confirm the efficacy of ETC complex II inhibition in glycolytic and OXPHOS-dependent leukemias in vivo and we also tested the combination of ETC complex II and lactate transporter inhibition in vivo in FLT3-ITD+ AML." (PMID 35440568, 2022). "Mechanistic studies of MV4-11 leukemia cells and HCT-116 colon cancer cells revealed that DBPR114 modulated FLT3 and AURKA/B targets inside the cells and induced the accumulation of multinucleated cells, which indicates mitotic checkpoint override through AURKB inhibition." (PMID 35062934, 2022). "Inhibition of ETC complex II did not impact on the leukemia development of glycolytic FLT3-wt HL60 cells." (PMID 35440568, 2022). "These involve genes which are known to be leukemia drivers (such as FAT1, NOTCH1, PHF6, FLT3), and can activate signaling pathways that push the cells to multiply faster, as well as genes involved in ribosome biogenesis or translational control (such as WDR36 and LTV1)." (PMID 36482893, 2022). "Moreover, it was able to eliminate FLT3-ITD quiescent and proliferating leukemia stem cells, as well as leukemic progenitors." (PMID 35065680, 2022). "Except for GSE17855, the archived datasets used in the present study did not contain information about the FLT3 status of the respective leukemia cases." (PMID 36627892, 2022). "For primary AML leukaemia blast with FLT3/ITD mutation, CD44v6 CAR‐T presented significant anti‐leukaemia effects but no obvious killing to the healthy donor, indicating the safety of normal myeloid cells." (PMID 36163632, 2022). "Researchers investigated the effect on leukaemia cells with wild-type FLT3, FLT3-ITD mutant, and no FLT3 receptor to add to their findings." (PMID 36615391, 2022). "Treatment was feasible even in the elderly and surprisingly effective in combination with Sorafenib (SOME), achieving 72% CR/Cri in R/R FLT3-ITDmut AML, 33% transplant rate, 43.6 weeks median overall survival and 22.4 weeks leukemia-free survival among responders." (PMID 36077850, 2022). "As a modular part of our nanocarrier system, siRNA can be designed and synthetized against any oncogenic factor and we here propose a targeted siRNA-transport system composed of an anti-CD33-antibody, protamine and siRNA that efficiently targets the leukemia-related oncogenes DNMT3A and FLT3." (PMID 36457063, 2022). "The nearly complete rescue from intervening in the FLT3-ITD-STAT5A pathway compared to the modest rescue from PRC2, suggests that the former is the predominant source of pinometostat-induced effects on proliferation in this leukemia background." (PMID 34263728, 2021). "Here we determined whether the FLT3-KIT short loop commonality, as well as other cases we identify in the leukaemia-specific networks, is supported by cellular functional data." (PMID 33709075, 2021). "However, this drug only modestly improved survival in FLT3/ITDpos AML patients, hence, there is still an unmet need for new drugs to treat this aggressive type of leukemia." (PMID 34002025, 2021). "Taken together, low dose MLL1 and DOT1L inhibitors downregulate different, yet partially overlapping sets of genes (with FLT3, MEF2C, and PIM1 in common), that are necessary for MLL-rearranged leukemia, consistent with the synergism arising from largely distinct pathways." (PMID 34263728, 2021). "To directly interrogate the effects of FLT3 on MLL-r leukemia proliferation without complications from different genetic backgrounds, we used viral transduction to insert a tet-inducible shRNA targeting FLT3 into MV4;11 cells." (PMID 34263728, 2021).
leukemia (continued). "It should be noted that a single treatment of DBPR114 is a multi-kinase inhibitor targeted for AML cell line through the FLT3 pathway, and the low-level anti-proliferative activity was detected in an FLT3-negative leukemia cell line." (PMID 34361230, 2021). "In this study, we demonstrated that unlike FLT3-wt (left), FLT3-ITD accumulates in early secretory organelles, such as the Golgi apparatus, and in that location, causes tyrosine phosphorylation signaling in leukemia cells (right)." (PMID 34811450, 2021). "Several novel agents such as DOT1L and FLT3 inhibitors that demonstrated selective targeting of KMT2A-r leukemia cells in preclinical models, have unfortunately failed to live up to their expectations in clinical trials." (PMID 35127484, 2021). "We observed a reduction in the viability of the FLT3-ITD heterozygous, non-MLL-rearranged leukemia cell line PL-21 after treatment with 10 μM pinometostat for 9 days, accompanied by a reduction in both FLT3 and PIM1 expression." (PMID 34263728, 2021). "Furthermore, FLT-3 PROTAC had good PK properties and can decrease FLT-3 protein in tumor tissues in a mouse model of MV4-11 leukemia." (PMID 32404196, 2020). "Low SIRT7 levels were always associated with active disease (nonhealthy conditions), in both BCR-ABL- and FLT3-ITD-positive leukemias." (PMID 32214204, 2020). "In patients with no mutations of both FLT3-ITD and NPM1, additional mutations in other leukemia-related genes proved to influence disease evolution." (PMID 32796597, 2020). "In mice with established FLT3-ITD-AML, LY2510924 induced durable mobilization and differentiation of leukemia cells, resulting in enhanced anti-leukemia effects when combined with quizartinib, whereas transient effects were seen on non-leukemic blood cells in immune-competent mice." (PMID 32629802, 2020). "Laboratory study showed that sorafenib in the post HSCT setting might increase serum IL-15 from residual FLT3-ITD cells that may enhance activities of allogeneic T-cells and graft-versus leukaemia effect." (PMID 32102366, 2020). "Thus, the interaction between FLT3-ITD-positive leukemia cells and bone marrow stroma via the stromal cell-derived factor-1 (SDF1)-CXCR-4 axis has the potential to enhance FLT3 inhibitor resistance." (PMID 33212779, 2020). "We found overexpression of Flt3-ITD did not provide additional proliferative advantage to the full-blown blastic phase leukemia K562 line or additional Mk differentiation propensity." (PMID 33363015, 2020). "This is because only FLT3(ITD)-positive leukemia cells, but not wild-type FLT3 AML cells, accumulate ROS-induced DSBs, but can survive due to the enhanced DNA repair activities." (PMID 31554189, 2019). "The authors have stated that VLA-4 activation by FLT3-ITD might contribute to FLT3-ITD-induced AML development with poor drug responsiveness and prognosis of this leukemia entity." (PMID 30841639, 2019). "Interestingly, lestaurtinib is cytotoxic to human AML cell lines expressing both mutant and wild-type FLT3, and it prolongs the survival of FLT3/ITD leukemia in a mouse model." (PMID 30514344, 2018). "Although overall FLT3-ITD status did not define the global leukemia metabolome, we identified multiple metabolic features with differential abundance between FLT3-ITD and FLT3-WT AML." (PMID 29615816, 2018). "We also performed CFU assays on the primary leukemia samples and normal BM MNC and observed significant decreases in the colonies formed in response to the combination vs. that of either drug alone only for the FLT3/ITD+ leukemic samples." (PMID 30250637, 2018).
leukemia (continued). "Similarly, FLT3-ITD AML cells demonstrate constitutively active AXL and AXL inhibition leads to decreased FLT3 phosphorylation and induction of leukemia cell death." (PMID 29806049, 2017). "However, the clinical effectiveness of FLT3 inhibitors in patients with AML was quite variable and, exhibited the modest clinical activity, and the clearance of peripheral leukemia blast cells." (PMID 29262547, 2017). "However, additional targeted SYK inhibition or dual FLT3/SYK inhibition potentiates the effects of midostaurin and other inhibitors of FLT3 against both kinase inhibitor-sensitive- and -resistant FLT3-ITD- and activated SYK-positive leukemia." (PMID 28881711, 2017). "BM-MSC samples isolated from mice bearing MLL/ENL leukemia, without FLT3 abnormality, were found to have a total of 1906 genes up-regulated and 1612 down-regulated, by at least 2-fold as compared to control BM-MSC." (PMID 29137349, 2017). "Given that FLT3-ITD-positive MV4-11 cells and FLT3-ITD-positive primary AML cells were observed to be especially sensitive to PI3KD/V-IN-01, we decided to investigate the in vivo effects of PI3KD/V-IN-01 using an in vivo model of mutant FLT3-positive leukemia." (PMID 27447747, 2016). "We explored the expression and functional link between FLT3 and main cytarabine transporters in 50 pediatric patients diagnosed with acute lymphoblastic leukemia and MLL rearrangement (ALL-MLL+) and other subtypes of leukemia, and in leukemia cell lines." (PMID 27391351, 2016). "Activating MEK mutations have not been discovered in leukemia, in which pathway activation is caused by mutations in upstream components such as RAS or Flt3." (PMID 27741509, 2016). "Having shown that TOPK inhibition exhibits preferential anti-leukemia activity in AML with FLT3-ITD, we speculated that TOPK expression or kinase activity is upregulated in FLT3-ITD cells compared to FLT3-wt cells." (PMID 26450903, 2015). "Because of the critical role played by CDK6 in MLL-rearranged AML and ALL, as well as in FLT3-ITD driven AML, CDK6 may be an effective therapeutic target in these leukemias." (PMID 25914884, 2015). "RAS mutations account for less than 10–15 % of pediatric AML and FLT3-ITD mutations do not exceed 5–8 %, which is in contrast with the higher frequency of MAPK/PI3K up-regulation observed in these leukemia." (PMID 26909356, 2015). "CD200 was more frequent in secondary compared to de novo leukemia (p = 0.0006), in CD34 positive cases (p = 0.00001), in Bcl2 overexpressing cases (p = 0.01), in those wild-type Flt3 (p = 0.004) and with favorable or unfavorable compared to intermediate karyotype (p = 0.0003)." (PMID 26338961, 2015). "It displays potent anti-cancer activity in models of FLT3-driven AML and considerable inhibitory ability to leukemia stem-like cells or leukemia-initiating cells (LICs) in Hoechst side population (SP) assays and long-term culture initiating cell (LTC-IC) assays." (PMID 26497577, 2015). "The results obtained in this study suggest that midostaurin shows its anti-cancer effect on AML by targeting not only FLT-3 but also Aurora kinases, especially in leukemia without aberration in FLT-3." (PMID 26141684, 2015).
leukemia (continued). "Finally, FLT3 internal tandem duplication (ITD), an independent prognostic factor for relapse in childhood AML, was detected in 8 children; leukemia cells of 5 of them (62%) were IDO-positive." (PMID 24903009, 2014). "While FLT3-ITD has certainly been demonstrated as a transforming lesion in multiple cell models and clearly contributes strongly to leukemogenesis, it is not sufficient to fully transform primary hematopoietic cells or generate leukemia in mouse models." (PMID 25295230, 2014). "Knock-in of heterozygous mutant ITD into murine FLT3 (FLT3+/ITD) causes a fatal MPD characterized by splenomegaly, leukocytosis, and myeloid expansion, but not frank leukemia." (PMID 25295230, 2014). "There is increasing evidence that FLT3-ITD has activity in hematopoietic stem cells, as demonstrated by the presence of ITD in the CD34+CD38− leukemia-initiating cell (LIC) population, and confirmation of the ITD mutation in these successfully engrafted LICs in a murine transplant model." (PMID 25295230, 2014). "This is underscored by the fact that no FLT3 inhibitors have been FDA-approved for the treatment of leukemia to date." (PMID 25295230, 2014). "The role of other FLT3 inhibitors, such as quizartinib, after stem cell transplant in FLT3-activating leukemia has not yet been addressed in the pediatric population." (PMID 25295230, 2014). "With either fusion genes, leukemia onset and progression, infiltration of peripheral organs or leukemia transplantability were unchanged in the absence of Flt3." (PMID 23977266, 2013). "FLT3 and c-Kit signaling direct MN1-expressing cells toward the myeloid lineage, so disruption of these signals may prevent leukemia." (PMID 24367366, 2013). "The survival curves of both cohorts (n = 9) were very similar indicating that Flt3 did not affect leukemia latency." (PMID 23977266, 2013). "The only feature that distinguished Flt3−/− and Flt3+/+MLL-ENL leukemia mice was a reduction in leukocytosis in the absence of Flt3." (PMID 23977266, 2013). "In the majority of these studies, the prognostic impact of FLT3 mutations on APL was evaluated in parallel with the white blood cell (WBC) count at diagnosis, a well known negative prognostic factor in these leukemias." (PMID 23936658, 2013). "We therefore assessed the expression of CD33 and FLT3 (data not shown) in the same 15 leukemia and cord blood samples in order to demonstrate correlation between the RPKM and delta Ct (dCt) values for this gene." (PMID 24069164, 2013). "All the leukemias were transplantable and induced similar disease regardless of their Flt3 status (and data not shown)." (PMID 23977266, 2013). "Finally, the FLT3/ITD-NHD13 model mimics the stepwise progression of a pre-leukemic disorder characterized by myelodyspasia, to overt leukemia that is frequently observed in patients." (PMID 22643831, 2012). "The presence of the AML1-ETO fusion protein in HSCs alone does not cause leukemia, as secondary genetic lesions ((like ICSBP deficiency, mutation in FLT3 and C-KIT) and/or potential leukemia supporting niche-effects are necessary for the progression to AML." (PMID 22363661, 2012). "To further investigate the FLT3 signaling pathway, we combined PhosphoScan®, with stable isotopic amino acids in cell culture (SILAC) to quantify changes in phosphorylation due to FLT3 inhibition in human leukemia cell lines." (PMID 21552520, 2011). "Furthermore, when we examined the PRL-3 protein expression in two isogenic leukemia cell lines, TF-1 and TF1-ITD (stable cell line transfected with FLT3-ITD cDNA), we found that the parental TF-1 cells were negative for PRL-3 protein." (PMID 21589872, 2011). "In addition, while these results may seem somewhat counterintuitive to the clinical findings that patients with FLT3 ITD leukemia experience worse overall survival and shorter disease-free remission, to date the presence of FLT3-ITD has not been associated with response to induction therapy." (PMID 21048955, 2010).
leukemia (continued). "This patient underwent a transformation to leukemia with AML/ETO fusion and acquisition of FLT3/ITD+, thereby corroborating Gilliland’s “two hit” hypothesis for leukemogenesis." (PMID 19466291, 2009). "Despite the important role of FMS-like tyrosine kinase 3/internal tandem duplication (FLT3/ITD+), a class I mutation, in providing a myeloproliferative signal and/or survival advantage to leukemia cells, this mutation does not affect differentiation by itself." (PMID 19466291, 2009). "Furthermore, response to gilteritinib, as defined by leukemia growth delay (LGD), was correlated with bulk FLT3 surface protein and gene expression, suggesting that FLT3 could be used as a predictive marker of response to gilteritinib in ETP-ALL." (PMID 39849166, 2025). "Importantly, menin’s interaction with both wild-type MLL and MLL fusion proteins is necessary to maintain oncogenic activation of Hox genes, as well as the Hox cofactors MEIS1 and PBX3, and downstream targets such as FLT3 in both MLLr and NPM1 mutant leukemias." (PMID 39336822, 2024). "Apoptosis induction in leukemia cells through USP14 inhibition has been previously documented; however, this is the first study to identify a specific mechanism by which USP14/UCHL5 inhibition induces apoptosis in FLT3-ITD-positive AML cells or in primary FLT3-ITD-positive AML cultures." (PMID 39408703, 2024). "We next determined the in vivo anti-leukemia efficacy of SNDX-50469 or SNDX-5613 and/or OTX015 in an aggressive and lethal MOLM13 xenograft model or in an AML PDX (PD xenograft) model expressing MLL-AF9 and FLT3-TKD, both models transduced with Luciferase/GFP for bioluminescence imaging." (PMID 37055414, 2023). "These efforts and additional validation experiments revealed PSIP1, CREBBP, and kinase FLT3 representing known vulnerabilities in KMT2A-r, as well as ARID4B, MBD3, and BMPR2 as potential candidates to be considered as novel therapeutic targets in this aggressive type of leukemia." (PMID 37686014, 2023). "To functionally assess the role of PDP1 in leukemia development in vivo, we transplanted (FLT3-ITD-positive) Molm13 cells transduced with either non-targeting control (NTC) or PDP1 shRNA expression vectors into immunocompromised NOD/SCID interleukin-2 receptor gamma knockout (NSG) mice." (PMID 37935978, 2023). "Previously, we found that TKI-treatment could activate a non-canonical NFKB2/Cytokines/Chemokines/CXCR2 pro-leukemia inflammatory pathway to initiate the survival and relapse of FLT3-mut AML blasts ex vivo." (PMID 38023123, 2023). "Similarly, the combination of menin inhibitors with FLT3 inhibitors resulted in an enhanced inhibitory effect on the proliferation and stimulatory induction of apoptosis of primary FLT3-mut leukemic blasts and of leukemia cells in a murine model of leukemia promoted by NPM1-mut and FLT3-ITD." (PMID 37509445, 2023). "FLT3-ITD lead to receptor dimerization and ligand-independent constitutive activation of downstream signal transduction pathways, such as mitogen-activated protein kinase (MAPK) signal transducer and activator of transcription 5 (STAT5), which maintain the leukemia cells proliferation." (PMID 38037057, 2023). "We generated a “switchable” system in which K-Ras mutant proteins expressed at physiologic levels supplant the fms like tyrosine kinase 3 (FLT3) dependency of MOLM-13 leukemia cells lacking endogenous KRAS and used this system to interrogate single or compound G12D, T50I, D154Q, and E162L mutations." (PMID 37681415, 2023). "have demonstrated that the combination of the CXCR4 antagonist LY2510924 and the FLT3 inhibitor quizartinib reversed the stroma-mediated resistance against the FLT3 inhibitor and induced the mobilization and differentiation of AML cells in mice, resulting in enhanced anti-leukemia effects." (PMID 37849810, 2023).